ARG1 (arginase 1)
Diseases named in the same sentence as ARG1 in open-access papers (continued):
Sharing a sentence is not in itself a finding about the gene and the disease.
cancer (continued). "RT-qPCR showed the expression of CHI3L1, IL-10, RETNLB (Fizz1), and Arg1, to confirm the M2 macrophages The results showed that the expression level of both CD68 and CD206 were significantly increased in cancer tissues compared with paracancerous tissues." (PMID 35637970, 2022). "MDSCs play a central role in cancer progression by mediating immunosuppression in the TME through a variety of mechanisms, including the production of inducible nitric oxide synthase (iNOS), arginase-1 (Arg1), oxygen free radicals (ROS), and nitric oxide (NO)." (PMID 34295338, 2021). "Expression of ARG1 is a defining feature of immunosuppressive myeloid cells that are highly enriched in the TME, and the role of ARG1-expressing MDSCs in altering T-cell responses in cancer patients is well established." (PMID 34504786, 2021). "ARG1, an enzyme constitutively expressed in PMNs and stored within intracellular granules, is a downstream target of activated STAT3, and in circulating MDSCs from cancer patients, STAT3 controls the immune suppressive activity." (PMID 35069595, 2021). "In combination with CALRmut-specific therapeutic cancer vaccination, these anti-regulatory vaccines have the potential to induce a clinical response, especially as patients with MPN harbor T cells specific to both PD-L1- and ARG-1-derived epitopes." (PMID 33718228, 2021). "Arg1 and iNOS were the markers of MDSC population activation, and the activated MDSCs could secrete IL6, IL8, and IL10 to enhance cancer progression." (PMID 32195173, 2020). "Another novel Arg1 and Arg2 inhibitor, OATD-02 by OncoArendi Therapeutics SA (undisclosed structure, IC50 < 50 nM), is also expected to enter phase I trials mid-2020 to evaluate its ability to inhibit the proliferation and immune escape of cancer cells." (PMID 32722521, 2020). "In addition, the local expression of key pathway enzymes (ARG1, ARG2, DDAH1, DDAH2, NOS2, ODC1, PRMT1, and PRMT5), as potential therapeutic targets, was evaluated in reference to cancer pathology." (PMID 32872669, 2020). "In this study, we found that cancer cells could induce an M2-like macrophage characterized by up-regulation of CD163 and Arg1, and down-regulation of IL-1b and IL-6 through Nrf2 activation." (PMID 30180849, 2018). "But, when we focused on the protein expression with fold-difference to adjacent noncancerous tissue or cancer tissue without PVT forming, FH, CA I, BHMT, IVD, CRAT, and arginase-1 were the six proteins which expressed deficiently in cancer cells with PVT." (PMID 28785178, 2017). "(F) qRT-PCR for Arg1 expression in macrophages cultured with control IMDM media or iKras* cancer cell conditioned media (CM) in presence or absence of DOX." (PMID 28980940, 2017). "In contrast, use of conditioned media from cancer cells treated with D-PDMP, an inhibitor of glucosylceramide synthase and lactosylceramide synthase, to inhibit ganglioside synthesis, resulted in the reduction of Arg-1 expression." (PMID 28032600, 2017). "The mRNA expression level of CD163 and ARG1 clearly decreased in cancer patients under chemotherapy regardless of the presence of bevacizumab, although bevacizumab accelerated the decrease of ARG1." (PMID 26840567, 2016). "Similarly, studies in cancer patients showed an expansion of CD14−CD15+CD11b+ G-MDSC population with the ability to inhibit T cell function via ROS- and arginase-1-dependent mechanisms." (PMID 24626392, 2014). "Expression of ARG1 was detected only in the cytoplasm of neutrophils by immunohistochemistry, and not in cancer cells." (PMID 23424623, 2013).
cancer (continued). "Thus, we inspected the gene expression levels of the examined genes (CD4, CD25, FOXP3, TGF-β, IFN-γ, IL-10, CTLA-4, PD-1, PD-L1, ARG1) in the CRC patients and confirmed they were all upregulated in the cancer patients." (PMID 22496728, 2012). "This might be due to Arg1 secretion and inadequate antigen presentation, leading to reduced CD8+ T cell proliferation, weakened T cell anticancer immunity, enhanced cancer growth, and temporary cancer cell proliferation." (PMID 40547943, 2025). "Notably, recent studies have shown that myeloid-specific Arg1 knockout alone is not sufficient to prevent cancer-induced wasting in mice, suggesting that additional factors are likely required to drive the full progression of muscle wasting." (PMID 40474277, 2025). "However, metastatic lymph nodes contained viable undifferentiated carcinoma cells that were negative for hepatocellular markers (HepPar-1 and arginase-1) but positive for CAM5.2 and vimentin, indicating a treatment-resistant component." (PMID 41415330, 2025). "In cancer, the corresponding signal transduction after PRR stimulation amplifies the effect of the immunosuppressive response of MDSCs by producing a variety of proteins, including arginase-1, iNOS, IDO-1, prostaglandin E2, PD-L1, CD40, TNF-α, IL-1β, IL-6, cyclooxygenase-2, and others." (PMID 39035356, 2024). "Additionally, MDSCs may enhance cancer immune escape via the deprivation of essential amino acids such as cysteine, arginine (Arg), and tryptophan (TRP) because they may express arginase-1 and indolamine 2,3-dioxygenase 1 (IDO1)." (PMID 37373581, 2023). "Indeed, we observed both in vivo and in vitro that depletion of PMN-MDSCs using cabozantinib resulted in the sensitization of cancer cells to anti-PD-1/PD-L1 treatment that correlated with significant decreases in NOS2 and Arg1 and increased CTL proliferation and effector function." (PMID 33348809, 2020). "Moreover, the Acetic acids/FFAR2 axis enhanced the expression of Arg1 through the Calcium/PPAR-γ pathway, suggesting inhibitors or modulators targeting Calcium/PPAR-γ or SCFA excess in combination with anti-PD-1 antibodies will have potential clinical value in improving cancer treatment." (PMID 38402237, 2024). "Moreover, the polarized macrophages express more vascular endothelial growth factor (VEGF) and arginase-1 (ARG-1), the former of which promotes blood vessel growth, while the latter catalyzes the production of polyamines, which facilitate the proliferation of cancer cells." (PMID 35454171, 2022). "Because EDA-FN increases arginase-1 mRNA expression and cancer growth, while inhibition of EDA-FN effects using the integrin α5β1 inhibitor diminishes arginase-1 and cancer growth, we sought to determine whether arginase indeed mediates EDA stimulation of cancer growth." (PMID 27653627, 2016). "For example, Arg-1 and PD-L1 have been suggested to have an important role in MDSC function in cancer, but their expression is not significantly increased in the MDSC subsets of late septic patients." (PMID 38385073, 2024). "MDSCs in cancer patients were characterized by the expression of CD14, CD11b, CD33, and Arg1, along with low or absent expression of HLA-DR." (PMID 37865804, 2023). "Interestingly, this signaling axis was not able to suppress the expression of arginase 1 (Arg1), a common immunosuppressive marker found in TAMs from many cancers, suggesting that other factors or other arms of the UPR may be necessary for TAMs to undergo a completely immunosuppressive program." (PMID 37067519, 2023). "CCLE analysis showed that CPS1 mRNA was expressed in some cancer cell lines, but most cancer cells did not express OTC and ARG1, implying the urea cycle was down-regulated in cancer cells." (PMID 33869206, 2021). "In this study, we also found that BHMT, IVD, CRAT and arginase-1 were all down-regulated in cancer tissues of HCC without PVT and further deceased in the cancer tissues of HCC with PVT." (PMID 28785178, 2017).
cancer (continued). "Betaine–homocysteine S-methyltransferase 1 (BHMT), isovaleryl-CoA dehydrogenase (IVD), short-chain specific acyl-CoA dehydrogenase (CRAT) and arginase-1 were all down-regulated in cancer tissues of HCC without PVT and further deceased in the cancer tissues of HCC with PVT." (PMID 28785178, 2017). "However, M2 ARG1 and IL-10 but not TGF-β expression levels increased with cancer progression." (PMID 40666494, 2025).
infection (262 papers, 2008 to 2026). The state of being infected such as from the introduction of a foreign agent such as serum, vaccine, antigenic substance or organism. "Studies have shown that during the polarization process of M1 macrophages caused by infection, the increase in histone lactylation at the promoter region induces the expression of homeostasis-related genes, including Arg1." (PMID 40665344, 2025). "Increased histone lactylation in promoter regions has been proven to induce the expression of homeostatic genes, including Arg1, during M1 macrophage polarization caused by infection." (PMID 33726814, 2021). "On the protein level, infection with S.tm alone already caused induction of ARG1 protein, which was further increased in the presence of IL-4, but suppressed by IFNγ." (PMID 34359992, 2021). "We also demonstrated that higher levels of Arg-1 at late infection periods modulate the disease outcome in susceptible mice, but the transference of macrophages from partially resistant mice (C57BL/6) restores the host protection and disease control." (PMID 34660334, 2021). "In the past, increased ARG1 activity has been linked to an impaired control of infections, especially with intracellular parasites." (PMID 34359992, 2021). "On the other hand, the expression of host cell Arg1 in highly Th2 polarized immune responses, such as infection of BALB/c mice, has been associated with parasite replication and susceptibility." (PMID 34557194, 2021). "M-MDSC acted as target cells for mycobacterial growth, created an inflammatory milieu prone to cause T cell suppression and aggravated the infection by the expression of Nos2 and Arg1." (PMID 30386330, 2018). "A Th2 immune response accompanied by AAM and Arg-1 is assumed to undermine the protective Th1 immune response against infections with trypanosmatids and thus contributes to susceptibility." (PMID 30555475, 2018). "Paradoxically, arginase-1 has been associated with enhancing infection with T. gondii by competing with iNOS for their common substrate L-arginine and promoting parasite replication by providing the polyamines needed for cell division." (PMID 23966857, 2013). "Rather, MKP-2−/− bone marrow-derived macrophages, as a consequence of increased Arginase-1 expression, were found to be inherently more susceptible to infection with L. mexicana than MKP-2+/+ derived macrophages." (PMID 23437409, 2013). "In contrast, the same strain of Arg1-deficient mice exposed to the same egg antigens by infection in similar time frames develop an exaggerated Th2 response in the liver and intestine." (PMID 23637937, 2013). "We show that during infection with L. major, enhanced Arginase-1 in MKP-2 deficient mice serves to induce a generalized T cell hypo-responsiveness so that IFN-γ and IL-4 levels are equally suppressed compared with intact mice." (PMID 23437409, 2013). "Whereas K. pneumoniae infection promoted NOS2 gene expression, infection by A. fumigatus caused increased Arg1 expression in the lung." (PMID 21246055, 2011). "In particular, MKP-2 deletion gives rise to a novel phenotype associated with decreased iNOS and increased arginase-1 activity which makes MKP-2 deficient macrophages more intrinsically susceptible to infection with the intracellular parasite L. mexicana." (PMID 21085614, 2010). "Additionally, CCL6 peaks on day 28 post-infection, which is likely associated with increased activation toward the M2 phenotype, responsible for the production of repair factors such as Arginase-1 and chitinase-like proteins." (PMID 40918106, 2025). "Therefore, it can be inferred that in response to pathogen infection, fish exhibit an inflammatory response, prompting arg1 upregulation to protect against tissue damage caused by inflammation." (PMID 39456653, 2024). "ARG1 upregulation is associated with increased pathogen load in different infection models." (PMID 37190073, 2023). "iNOS was more commonly associated with infection than Arg1+ macrophages." (PMID 35682679, 2022).
infection (continued). "Infection with S.tm caused an upregulation of Arg1 in BMDM of both genotypes." (PMID 34359992, 2021). "Arg1 is a cytosolic enzyme expressed in macrophages, myeloid-derived suppressor cells (MDSCs), DCs and innate lymphoid group 2 cells in response to Th2-type cytokines (IL-4, IL-13), and to other signalling factors associated to pathogens infection." (PMID 34163018, 2021). "Notably, at the later period (9 months post-infection), reduced CD3ζ was associated with elevated ARG-1 expression and a significantly decreased l-arginine concentration in serum." (PMID 32029006, 2020). "Similarly, we found that neutralization of Arg1 decreased bacterial clearance in Stat2−/− mice during super-infection in association with an attenuated number of iNOS+Arg1+ dual function macrophages." (PMID 30337919, 2018). "We hypothesized that macrophage polarization may have been impacted by the presence of Tlr7 and measured Arginase 1 (Arg1), a marker of macrophage phenotype, finding that expression was significantly increased upon infection in Tlr7-deficient BMMs." (PMID 29616197, 2018). "Previous data have shown that loss of Arg1 leads to improved mycobacterial host defense early, but allows T cell-mediated immunopathology in late stages of infection, reminding us that regulating a balance of activation and inhibition is a key property during immune responses." (PMID 29201027, 2017). "While highlighting the importance of iNOS and NO production in controlling T. gondii infection, the present study also uncovered a protective role for arginase-1 in controlling parasite multiplication that can compensate for NO deficiency during early infection." (PMID 23966857, 2013). "Competition of Arg1-expressing macrophages with myofibroblasts for the substrate L-Arg causing less collagen production by the myofibroblasts has been suggested as one possible mechanism for suppression of fibrosis by AAMs induced after infection by S. mansoni." (PMID 21246055, 2011). "However, analysis of cytokine responses, antibody titres and pathological indicators, including collagen staining, crypt cell hyperplasia, and goblet cell hyperplasia, failed to reveal any differences between mice with deficient Arg1 function in AAMs and wild-type controls post-infection." (PMID 21585399, 2011). "Upon Ld-Infection, iNOS2 expression was diminished by 1.56-fold (p ≤ 0.01), and Arginase-1 expression was upregulated by 3.86-fold (p ≤ 0.01)." (PMID 41339683, 2025). "This indicates that the decrease in CD73 expression on dMφ after infection regulates the expression of Arg-1 and IL-10 by influencing the binding of Ado to A2AR." (PMID 39994736, 2025). "SA infection also significantly decreased Arg1 expression (L2FC = −0.99, P = 0.0145) but increased Il10 expression (L2FC = 1.78, P = 0.0009)." (PMID 41025812, 2025). "In vivo, flow cytometry revealed that the percentage of Arg-1 positive cells in mouse dMφ were decreased after infection (P < 0.01) and further reduced in dMφ from CD73−/− infected pregnant mice (P < 0.05)." (PMID 39994736, 2025). "In the case of nasal TES administration, increased expression was observed only at 3 dpfi, while in the infection model, elevated expression of Arginase-1 and Chil3L3 persisted throughout all experiment time points." (PMID 40918106, 2025). "Infection with T. spiralis led to a significant increase in arginase-1 and TNF-α gene expression, whereas the relative expression of IL-10 significantly decreased." (PMID 41239511, 2025). "Infection with T. spiralis significantly increased the expression of the arginase-1 gene as compared to uninfected mice (P < 0.05)." (PMID 41239511, 2025). "Mechanistically, Leishmania-derived EVs are enriched with polyamines, which are efficiently captured by macrophages, leading to higher infection rates and increased expression of Arginase 1, a known M2 marker." (PMID 40981465, 2025). "Arg1 expression was dependent on IL-4, which was present in the lung at low levels before infection." (PMID 40854598, 2025).